GPR171 (G protein-coupled receptor 171)
Description:
G protein-coupled receptor for Big LEN, a 16-amino acid neuropeptide produced from the precursor protein, proSAAS (encoded by PCSK1N). Acts through a G(i)-alpha-mediated pathway in response to Big LEN. Big LEN-GPR171 system plays an important role in regulating feeding and metabolism. Also plays a role in modulating fear and anxiety-like behaviors in the basolateral amygdala. Big LEN-GPR171 modulates the mu-type opioid receptor signaling and antinociception (By similarity). Acts as a negative regulator T cell function.
Synonyms: H963
Tractability: Small molecule: it belongs to a druggable protein family. Antibody: UniProt places it where antibodies can reach, with medium confidence; UniProt predicts a signal peptide or a membrane-spanning region; its Gene Ontology location is reachable by antibodies, with medium confidence; the Human Protein Atlas places it where antibodies can reach.
Target class: Family A G protein-coupled receptor; Membrane receptor
Gene: Protein-coding gene on chromosome 3 (151,197,832 to 151,203,216, reverse strand). Ensembl gene ENSG00000174946.
Subcellular location: Cell membrane
Subcellular location (Human Protein Atlas): Plasma membrane; Vesicles
Gene Ontology:
Molecular function: protein binding; G protein-coupled peptide receptor activity; G protein-coupled purinergic nucleotide receptor activity; G protein-coupled receptor activity; neuropeptide binding; neuropeptide receptor activity
Biological process: adenylate cyclase-inhibiting G protein-coupled receptor signaling pathway; adenylate cyclase-modulating G protein-coupled receptor signaling pathway; G protein-coupled receptor signaling pathway; regulation of feeding behavior; regulation of sensory perception of pain; G protein-coupled purinergic nucleotide receptor signaling pathway; neuropeptide signaling pathway
Cellular component: plasma membrane; membrane
Genetic constraint (gnomAD): Loss-of-function variants: 17 observed, 21.43 expected, observed/expected ratio (o/e) 0.79, 90% interval 0.54 to 1.19. The upper end of that interval is the gene's LOEUF score, 1.19, which puts it in group 5 of 6, group 1 being the genes least tolerant of losing a copy. Missense variants: 337 observed, 397.78 expected, observed/expected ratio (o/e) 0.85, 90% interval 0.77 to 0.93. Synonymous variants: 134 observed, 143.37 expected, observed/expected ratio (o/e) 0.93, 90% interval 0.81 to 1.08.
Homologues: Orthologues: chimpanzee GPR171 (100% identical), macaque GPR171 (99% identical), rabbit GPR171 (91% identical), dog GPR171 (91% identical), pig GPR171 (90% identical), mouse Gpr171 (90% identical), rat Gpr171 (89% identical), guinea pig GPR171 (87% identical), tropical clawed frog gpr171 (64% identical), zebrafish gpr171 (48% identical). Paralogues in human: P2RY12 (32% identical), P2RY14 (32% identical), P2RY13 (31% identical), GPR87 (26% identical), GPR34 (25% identical), PTAFR (24% identical).
Diseases named in the same sentence as GPR171 in open-access papers:
GPR171 is named in the same sentence as 36 diseases in open-access papers, as found by Europe PMC text mining. Sharing a sentence is not in itself a finding about the gene and the disease. The quoted sentences say what the papers report.
Anxiety (2 papers, 2021 to 2023). Intense feelings of nervousness, tension, or panic often arise in response to interpersonal stresses. "GPR171 is a G-protein-coupled receptor, which regulates feeding and anxiety behaviors by binding to its neuropeptide ligand, BigLen." (PMID 37894456, 2023). "The recently identified G-protein-coupled receptor GPR171 and its ligand BigLEN are thought to regulate food uptake and anxiety." (PMID 34615877, 2021).
asthma (2 papers, 2021 to 2025). "Further, extreme temperature fluctuations consistently led to decreased expression of Wfdc21, Cib3, Gpr171, and Cttnbp2 in mice and asthma patients." (PMID 40313552, 2025). "Adult asthma subjects in the extreme temperature fluctuation group showed consistently decreased Wfdc21, Cib3, Gpr171, and Cttnbp2 expression, while increased Tiam2 and Cma1 expression." (PMID 40313552, 2025). "We observed that the mild, moderate, and severe asthma subject in the extreme low temperature group showed increased Tob1, Mub2, Sic34a2, Sftpc, Nxnl, Luc71, Lamp3, Gpr171, Cox14, and Cd3e expression, while in the severe asthma subjects showed increased expression in all temperature exposure group." (PMID 40313552, 2025). "In addition, asthma subjects in the extreme temperature fluctuation group showed decreased expression of Wfdc21, Cib3, Gpr171, and Cttnbp2, while Tiam2 and Cma1 expression increased." (PMID 40313552, 2025). "Additionally, subjects with severe asthma were more sensitive to low, high temperature and temperature fluctuation conditions, with increased of Tob1, Mub2, Sic34a2, Sftpc, Nxnl, Luc71, Lamp3, Gpr171, Cox14, and Cd3e expression." (PMID 40313552, 2025).
lung carcinoma (2 papers, 2016 to 2020). "Depletion of GPR171 causes an increase in food intake, providing a provocative link to the lung cancer-protective effect of being overweight suggested by meta-analyses." (PMID 26760963, 2016). "Studies have shown that GPR171 enhanced proliferation and metastasis of lung cancer in an EGFR-independent manner." (PMID 33050301, 2020). "Depletion of GPR171 with an anti-GPR171 antibody decreased proliferation of lung carcinoma cells and attenuated tumor progression in a mouse xenograft model." (PMID 26760963, 2016). "Of 47 lung cancer tissues, 22 (46.8%) were positive for GPR171; of 35 NSCLC specimens, 16 (45.7%) stained positively for GPR171 expression." (PMID 26760963, 2016). "Further studies are needed to verify the mechanism by which GPR171 promotes proliferation and metastasis in lung cancer and to apply it for the development of a new anticancer drug." (PMID 26760963, 2016). "To further confirm that GPR171 is indeed overexpressed in lung cancers, we searched for GPR171 gene alterations in lung tumors using the cBioPortal for cancer genomics." (PMID 26760963, 2016). "Immunostaining of clinical samples indicated that GPR171 was overexpressed in 46.8% of lung carcinoma tissues." (PMID 26760963, 2016). "Having demonstrated that GPR171 is preferentially expressed in various lung cancer tissues, we next sought to confirm a functional role of GPR171 in lung cancer using an RNA interference approach." (PMID 26760963, 2016). "Specifically, we demonstrated that GPR171, also known as platelet-activating receptor H963, is a tumor-promoting gene that induces proliferation, invasion, and migration of lung cancer cells in an EGFR-independent manner." (PMID 26760963, 2016). "This preferential expression in cancer tissues, which is central to the issue of clinical relevance, suggests that GPR171 is a pro-tumorigenic target in lung cancer." (PMID 26760963, 2016). "The inhibition of cancer cell proliferation observed after knocking down GPR171 with shRNA or siRNA, or inhibiting it with a blocking antibody suggests that GPR171 is a promising anti-cancer target in lung cancer." (PMID 26760963, 2016). "The immunohistochemisty analysis showed that GPR171 was expressed in various lung cancer tissues, but was rarely detected in normal bronchial epithelium." (PMID 26760963, 2016). "Mesenchymal-like NSCLC cells evince aberrant PDGFR and FGFR expression and autocrine signalling through these receptors can activate the MEK-ERK and PI3K pathways.Another GPCR family member, GPR171, identified as a potential tumour-promoting gene, is also overexpressed in lung cancer." (PMID 33050301, 2020). "Next, we investigated whether GPR171 siRNAs targeting other sites in the GPR171 sequence inhibited A549 (lung carcinoma) cell proliferation." (PMID 26760963, 2016). "We identified a previously unrecognized role of GPR171 in lung cancer tumorigenesis." (PMID 26760963, 2016). "Our findings suggest that GPR171 could be another crucial tumorigenesis signaling pathway in lung cancer." (PMID 26760963, 2016). "Knockdown of GPR171 also inhibited migration and invasion of the lung cancer cell lines." (PMID 26760963, 2016). "Notably, inhibition of GPR171 synergistically enhanced the tumoricidal activity of an epidermal growth factor receptor (EGFR) inhibitor in lung cancer cells." (PMID 26760963, 2016). "Therefore, the presence of BigLEN might be a key to the tumorigenesis of lung cancer, and activation of GPR171, as well as the level of GPR171, might contribute to tumorigenesis." (PMID 26760963, 2016). "Collectively, these findings indicate that combined inhibition of GPR171 and EGFR may be a promising strategy for lung cancer treatment, reflecting the fact that GPR171 induces tumorigenesis in an EGFR-independent manner." (PMID 26760963, 2016).
lung carcinoma (continued). "To determine if GPR171 exerts its tumor-promoting activity via an EGFR-dependent pathway, we compared GPR171 expression patterns with EGFR phosphorylation patterns (p-EGFR) in 47 lung cancer specimens using immunohistochemistry." (PMID 26760963, 2016). "Through a bioinformatics approach, we identified GPR171, a member of the class A rhodopsin superfamily, specifically the P2Y12 family, as a potential tumor-promoting gene that enhanced proliferation and metastasis of lung cancer." (PMID 26760963, 2016).
adenosquamous carcinoma (1 paper, 2016). A carcinoma composed of malignant glandular cells and malignant squamous cells. "Among NSCLC subtypes, squamous cell carcinoma, bronchioloalveolar carcinoma, adenosquamous carcinoma, and large-cell carcinoma exhibited a relatively high frequency of positive immunostaining for GPR171, whereas mucoepidermoid carcinoma did not." (PMID 26760963, 2016).
autoimmune thyroid disease (1 paper, 2022). Inflammatory disease of the thyroid gland due to autoimmune responses leading to lymphocytic infiltration of the gland. "Moreover, genomes associated with allograft rejection, autoimmune thyroid disease, and graft-versus-host disease signaling were differentially enriched in the GPR171 high-expression phenotype." (PMID 36212434, 2022). "In addition, GSEA analysis showed that DIRAS3, GPR171, and RAC2 are involved in signaling pathways such as ECM–receptor interaction, complement and cohesion cascades, adhesion plaques, allograft rejection, autoimmune thyroid disease, graft-versus-host disease, and cell adhesion molecules." (PMID 36212434, 2022).
breast carcinoma (1 paper, 2022). "In conclusion, the expressions of DIRAS3, GPR171, and RAC2 genes associated with brain metastasis were reduced in metastatic breast cancer and were strongly associated with overall breast cancer survival." (PMID 36212434, 2022). "The expression of DIRAS3, GPR171 and RAC2, genes associated with brain metastasis, was reduced in metastatic breast cancer, and GPR171 was found to promote brain metastasis of breast cancer cells by inducing B cells and thereby." (PMID 36212434, 2022). "Our study also showed that the expression level of GPR171 was significantly correlated with B cells, suggesting that GPR171 could promote brain metastasis of breast cancer cells by inducing B cells." (PMID 36212434, 2022). "The analysis showed that GBP2 was not significantly different from the overall survival of breast cancer patients, while GPR171, DIRAS3, and RAC2 were strongly associated with the overall survival of breast cancer patients." (PMID 36212434, 2022). "Therefore, we speculate that GPR171 could promote brain metastasis of breast cancer cells by inducing B cells, but the exact mechanism remains to be investigated." (PMID 36212434, 2022). "Expression difference analysis showed that GBP2, GPR171, DIRAS3, and RAC2 were significantly down-regulated in expression in metastatic breast cancer compared with primary breast cancer tumors." (PMID 36212434, 2022). "Only GPR171, DIRAS3, and RAC2 were strongly correlated with the overall survival of breast cancer patients." (PMID 36212434, 2022). "The analysis showed that only GBP2, GPR171, DIRAS3, and RAC2 were significantly down-regulated in expression in metastatic breast cancer compared with primary breast cancer tumors." (PMID 36212434, 2022). "We performed expression analyses of five genes (GBP2, GPR171, DIRAS3, RAC2, CACNA1D) obtained from the LASSO model to observe their expressions in primary breast cancer and metastatic breast cancer." (PMID 36212434, 2022). "To further explore the biological pathways most relevant to the pathogenesis of breast cancer brain metastasis, we performed GSEA analysis on GPR171, DIRAS3, and RAC2." (PMID 36212434, 2022). "Notably, in the present study, our results also showed that DIRAS3, GPR171, and RAC2 were less expressed in tumors that developed metastatic disease compared with primary breast cancer tumors." (PMID 36212434, 2022). "Moreover, the expression levels of DIRAS3, GPR171, and RAC2 were strongly correlated with the overall survival of breast cancer patients." (PMID 36212434, 2022).
colon cancer (1 paper, 2021). "To extend our observations to other mouse tumor models, we assessed the antitumor effect of GPR171 antagonist in mice subcutaneously implanted with B16-OVA or CT26 (colon cancer)." (PMID 34615877, 2021). "In MC38 colon cancer, the treatment of GPR171 antagonist right after MC38 inoculation significantly retarded tumor growth; as a result, 18 days after tumor inoculation, tumor weight in the GPR171 antagonist-treated group was only about 40% of the control group." (PMID 34615877, 2021).
fibromyalgia (1 paper, 2021). A chronic disorder of unknown etiology characterized by pain, stiffness, and tenderness in the muscles of neck, shoulders, back, hips, arms, and legs. "In addition, the increase in the endogenous ligand ProSAAS, seen in circulating CSF of fibromyalgia patients, is likely a consequence of adaptations toward restoring GPR171 signaling as we have observed a decrease in brain-specific GPR171 receptor expression in males with neuropathic pain." (PMID 35295419, 2021).
Hypertension (1 paper, 2025). The presence of chronic increased pressure in the systemic arterial system. "Although there is currently no research reporting the association of the genes P2RY10, GPR171, KLC3, and LYSMD3 with hypertension, these genes may indirectly affect the occurrence of hypertension." (PMID 39854379, 2025).
lung anaplastic carcinoma (1 paper, 2016). "To determine if GPR171 has a role in cellular proliferation, we examined the growth rates of an NSCLC cancer cell line, Calu-6 (lung anaplastic carcinoma), expressing one of two different small hairpin RNAs (shRNAs) against GPR171 or control shRNA." (PMID 26760963, 2016).
lung squamous cell carcinoma (1 paper, 2016). "Interestingly, we found increased gene copy numbers rather than mutations of GPR171 in lung squamous cell carcinoma and adenocarcinoma." (PMID 26760963, 2016).
melanoma (1 paper, 2021). A malignant, usually aggressive tumor composed of atypical, neoplastic melanocytes. "On the other hand, GPR171 transcription in human melanoma was upregulated in response to immunotherapy." (PMID 34615877, 2021). "Based on early published databases, GPR171 expression tends to be upregulated in tumor-infiltrating lymphocytes (TILs) and its expression in melanoma patients is significantly increased in response to immunotherapies." (PMID 34615877, 2021). "Finally, we tested whether GPR171 blockade can sensitize immunotherapy in established B16F10 melanoma, a poorly immunogenic tumor resistant to ICB therapy." (PMID 34615877, 2021).
neuropathic pain (1 paper, 2021). Chronic pain caused by damage to nerve fibers. "The decrease in GPR171 protein levels in the vlPAG following neuropathic pain is comparable to reports of decreased mu opioid receptor availability following chronic pain." (PMID 35295419, 2021).
Obesity (1 paper, 2016). Accumulation of substantial excess body fat. "The only previously known function of GPR171 is its involvement in feeding and metabolism; thus, GPR171 has been suggested as a potential target for anti-obesity therapeutics." (PMID 26760963, 2016).
ovarian tumors (1 paper, 2016). "GPR171 was overexpressed in subsets of breast, liver, lung, and ovarian tumors, along with a subset of cancer cell lines from the lung." (PMID 26760963, 2016).
squamous cell carcinoma (1 paper, 2016). A carcinoma arising from squamous epithelial cells. "Moreover, Gpr171 was highly expressed in the invading front of squamous cell carcinoma as well as in cells metastatic to the lymph node." (PMID 26760963, 2016).
T-cell leukemia (1 paper, 2021). A malignant disease of the T-lymphocytes in the bone marrow, thymus, and/or blood. "Consistently, our western blot result indicated that Jurkat cells, a human T-cell leukemia line, and normal PBMCs both expressed significant amount of GPR171 protein." (PMID 34615877, 2021).
virus infection (1 paper, 2016). "Considering that 7-12 weeks are required for significant body weight changes after GPR171 shRNA virus infection, we cannot exclude the possibility of a link between GPR171 and body weight." (PMID 26760963, 2016).